ABCB11 (ATP binding cassette subfamily B member 11)
Description:
Catalyzes the transport of the major hydrophobic bile salts, such as taurine and glycine-conjugated cholic acid across the canalicular membrane of hepatocytes in an ATP-dependent manner, therefore participates in hepatic bile acid homeostasis and consequently to lipid homeostasis through regulation of biliary lipid secretion in a bile salts dependent manner. Transports taurine-conjugated bile salts more rapidly than glycine-conjugated bile salts. Also transports non-bile acid compounds, such as pravastatin and fexofenadine in an ATP-dependent manner and may be involved in their biliary excretion.
Synonyms: BSEP; ABC16; SPGP; PFIC-2; PGY4; BRIC2; PFIC2
Tractability: Small molecule: a structure with a bound ligand is known; a high-quality ligand is known. Antibody: UniProt places it where antibodies can reach, with high confidence; its Gene Ontology location is reachable by antibodies, with high confidence; UniProt predicts a signal peptide or a membrane-spanning region. PROTAC: UniProt records ubiquitination sites on it; its protein half-life has been measured; a small molecule that binds it is known.
Target class: ATP-binding cassette; ABCB subfamily; Transporter; Primary active transporter
Gene: Protein-coding gene on chromosome 2 (168,915,498 to 169,031,324, reverse strand). Ensembl gene ENSG00000073734.
Subcellular location: Apical cell membrane; Recycling endosome membrane; Endosome; Cell membrane
Subcellular location (Human Protein Atlas): Cytosol; Nucleoplasm; Plasma membrane
Pathways (Reactome):
Metabolism: Recycling of bile acids and salts; Synthesis of bile acids and bile salts via 7alpha-hydroxycholesterol
Disease: Defective ABCB11 causes PFIC2 and BRIC2
Gene Ontology:
Molecular function: ABC-type bile acid transporter activity; ABC-type xenobiotic transporter activity; bile acid transmembrane transporter activity; canalicular bile acid transmembrane transporter activity; protein binding; ABC-type transporter activity; ATP binding; ATP hydrolysis activity
Biological process: bile acid and bile salt transport; bile acid metabolic process; canalicular bile acid transport; protein ubiquitination; xenobiotic export from cell; xenobiotic metabolic process; xenobiotic transmembrane transport; bile acid biosynthetic process; cholesterol homeostasis; fatty acid metabolic process; lipid homeostasis; phospholipid homeostasis; positive regulation of bile acid secretion; regulation of fatty acid beta-oxidation; transmembrane transport
Cellular component: apical plasma membrane; cell surface; extracellular exosome; plasma membrane; basolateral plasma membrane; endosome; intracellular canaliculus; recycling endosome; recycling endosome membrane; apical part of cell; intercellular canaliculus; membrane
Genetic constraint (gnomAD): Loss-of-function variants: 77 observed, 126.01 expected, observed/expected ratio (o/e) 0.61, 90% interval 0.51 to 0.74. The upper end of that interval is the gene's LOEUF score, 0.74, which puts it in group 3 of 6, group 1 being the genes least tolerant of losing a copy. Missense variants: 1,377 observed, 1,505 expected, observed/expected ratio (o/e) 0.91, 90% interval 0.87 to 0.96. Synonymous variants: 522 observed, 519.31 expected, observed/expected ratio (o/e) 1.01, 90% interval 0.94 to 1.08.
Homologues: Orthologues: chimpanzee ABCB11 (99% identical), macaque ABCB11 (97% identical), rabbit ABCB11 (90% identical), dog ABCB11 (90% identical), pig ABCB11 (89% identical), guinea pig ABCB11 (85% identical), rat Abcb11 (82% identical), mouse Abcb11 (82% identical), tropical clawed frog abcb11.2 (73% identical), zebrafish abcb11b (70% identical), Caenorhabditis elegans pgp-1 (39% identical), Caenorhabditis elegans pgp-9 (38% identical), and 7 more. Paralogues in human: ABCB1 (49% identical), ABCB4 (48% identical), ABCB5 (44% identical), ABCB9 (17% identical), ABCB10 (16% identical), ABCB8 (15% identical), ABCB6 (15% identical), TAP2 (14% identical), TAP1 (14% identical), ABCB7 (13% identical).
Diseases named in the same sentence as ABCB11 in open-access papers:
ABCB11 is named in the same sentence as 129 diseases in open-access papers, as found by Europe PMC text mining. Sharing a sentence is not in itself a finding about the gene and the disease. The quoted sentences say what the papers report.
cholestasis (215 papers, 2009 to 2026). Impairment of the bile flow caused by obstruction within the liver, or outside the liver in the bile duct system. "If a deficiency in BSEP were the major cause of MYO5B-associated cholestasis, we would expect the clinical parameters of MYO5B-associated and ABCB11 deficiency-associated cholestasis to be similar." (PMID 41511375, 2026). "The prevailing theory for the mechanism underlying MYO5B-associated cholestasis implicates faulty trafficking of the ABCB11-encoded bile salt export pump (BSEP) in hepatocytes due to dysfunctional myosin-Vb." (PMID 41511375, 2026). "We compared the serum biochemistry and clinical data of MYO5B-associated cholestasis with data from the ABCB11 deficiency-associated cholestasis database (NAPPED)." (PMID 41511375, 2026). "Together, disease parameters from the MYO5B-associated and ABCB11 deficiency-associated cholestasis cohorts displayed significant differences, indicating a potentially distinct underlying cause." (PMID 41511375, 2026). "Nonetheless, only 6% of MYO5B-associated cholestasis cases underwent liver transplantation before the age of five years, less than reported for ABCB11 deficiency-associated cholestasis (FIC1/1 10%, FIC3/3 60% and FIC1/3 85%)." (PMID 41511375, 2026). "Homozygous variants of ABCB4 and ABCB11 genes, bile constituent transporters, can lead to severe cholestasis." (PMID 40022113, 2025). "Loss of BSEP function in PFIC2 leads to cholestasis and intrahepatic accumulation of bile acids, the native toxicity of which drives progressive liver injury, in a manner that correlates with ABCB11 genotype." (PMID 40513781, 2025). "Mutations in the ABCB11 gene are responsible for several different genetic forms of cholestasis: PFIC2, formerly known as Byler’s syndrome, BRIC2, and other acquired forms of cholestasis." (PMID 36982896, 2023). "Homozygous mutations in ABCB4 and ABCB11 cause a spectrum of disease from mild cholestasis to severe progressive familial intrahepatic cholestasis (PFIC), PFIC3 and PFIC2 respectively." (PMID 37208429, 2023). "Mutations in BRIC (ATP8B1 and ABCB11) cause cholestasis by disrupting the Bile Salt Export Pump (BSEP), which transports bile to the canaliculi." (PMID 35310310, 2022). "We also reported on four female teenagers who presented a first episode of normal GGT cholestasis when started with an oestroprogestative drug and in whom a mono-allelic P or LP variant of ABCB11 was identified." (PMID 35626323, 2022). "In this review, we will focus on the molecular structure of ABCB11, reported mutations involved in cholestasis and current treatment options for inherited BSEP deficiencies." (PMID 33466755, 2021). "Cholestasis often results from the direct inhibition of hepatocellular canalicular transporters involved in the efflux of BAs, such as the bile salt export pump (BSEP, ABCB11) and multidrug resistance-associated protein (MRP) 2 (ABCC2)." (PMID 34681664, 2021). "We report on a newly-identified heterozygous ABCB11 missense variant (c.1345G > A, p.Glu449Lys) which was associated with prolonged cholestasis in a term infant after a complicated neonatal period." (PMID 32646411, 2020). "Conversely, mice deficient in the IL-1 receptor showed increased FXR binding and decreased NF-κB binding to the Abcb11 promoter, which was associated with normalized Abcb11 expression and attenuation of cholestasis." (PMID 29643332, 2018). "When a small group of patients suffered DILI after a series of drug administrations, a report indicated that a polymorphism in the exon region of the ABCB11 was associated with cholestasis injury." (PMID 29221149, 2017). "One of the most common causes of drug-induced cholestasis is the inhibition of the bile salt export pump (ABCB11 or BSEP)." (PMID 28391356, 2017). "Genetic analysis for mutations in the ABCB11 gene can aid in diagnosis after ruling out common causes of cholestasis." (PMID 24991443, 2014).
cholestasis (continued). "Because of continued jaundice and cholestasis, genetic testing was done, showing mutations in the ABCB11 gene (c.890A>G; p.Q297G/c.2343+1 G>T), confirming the diagnosis of PFIC type 2." (PMID 24991443, 2014). "Mutations in ATP8B1 (PFIC1/FIC1 deficiency) and ABCB11 (PFIC2/BSEP deficiency) may cause either BRIC1/BRIC2 or progressive cholestasis with severe pruritus." (PMID 41601986, 2026). "ABCB11 variants presented as acute/episodic cholestasis (40%) or ICP (82.4%)." (PMID 39984942, 2025). "Additionally, we present phenotypic validation of a novel knockin mouse model of the cholestasis-associated ABCB11 E297G variant." (PMID 40513781, 2025). "Moreover, drugs inhibiting ABCB11 are also associated with the possible occurrence of drug-induced cholestasis." (PMID 39132058, 2022). "Further, growing evidence suggests that genetic alterations in ABCB11 may predispose individuals to drug-induced cholestasis." (PMID 30023358, 2018). "Finally, mutations in the ABCB11 gene can often cause different phenotypes of cholestasis in the same patient: in addition to DIC, ICP, PFIC, BRIC, and LPAC may be present." (PMID 36982896, 2023). "Although there has been no clear evidence linking this variant with susceptibility to BA, the results of genetic analysis about the genetic correlation of ABCB11 variant p.Val444Ala with BA raised the hypothesis that cholestasis may be the cause of severe inflammatory cholangiopathy in BA." (PMID 34964797, 2021). "The mechanism underlying MYO5B-associated cholestasis has been attributed to abnormal localization of BSEP in liver cells, essentially mimicking ABCB11 deficiency-associated FIC." (PMID 41511375, 2026). "Of these, MYO5B-associated cholestasis (OMIM#619868) emerges as a considerable group, estimated to represent up to 25% of FIC cases other than those caused by variations in the ATP8B1, ABCB11 and ABCB4 genes." (PMID 41511375, 2026). "A cholestasis gene panel revealed an autosomal recessive variant in the ABCB11 gene, which encodes a bile salt export pump and is associated with benign recurrent intrahepatic cholestasis (BRIC)." (PMID 40486902, 2025). "Based on the current findings, it is only effective for cholestasis caused by the UGT1A1, ABCB11, and ABCC2 gene mutations." (PMID 39981091, 2025). "Among the 356 adult patients of a study on variants in cholestasis-related genes in adults, 101 were identified as carriers of variants of the genes ATP8B1, ABCB11, and ABCB4, often in heterozygosity." (PMID 39984942, 2025). "PFIC can present in an episodic form characterized by intermittent cholestatic attacks; episodic cholestasis can also be caused by mutations in PFIC-associated genes (e.g., ATP8B1 and ABCB11)." (PMID 39768432, 2024). "Mutations in genes encoding bile transport proteins such as ATP8B1 (PFIC1) and ABCB11 (PFIC2), and tight junction protein ZO-2 (PFIC4), can disrupt bile flow regulation and contribute to cholestasis." (PMID 39322562, 2024). "Homozygous variants or compound heterozygous variants in ABCB4 and ABCB11 can cause a spectrum of disease from moderate cholestasis to severe progressive familial intrahepatic cholestasis (PFIC), PFIC3 and PFIC2 respectively." (PMID 39262913, 2024). "The induction of cholestasis was verified by the gene expression changes in two well‐established cholestasis markers: Abcb11/Bsep, the main apical bile acid exporter, and Cyp7a1/Cyp7, a rate‐limiting enzyme in bile acid synthesis." (PMID 37522754, 2023). "In the mouse PNAC model, antagonism of HNF4a decreased NFκB binding to the Abcb11 promoter, normalized Abcb11 expression and attenuated cholestasis." (PMID 37173326, 2023). "The results showed a correlation between two nonsynonymous p.D676Y and p.G855R mutations in ABCB11 and DIC (drug-induced cholestasis)." (PMID 36982896, 2023).
cholestasis (continued). "For example, mutations in ABCB11, which encodes bile salt export pump (BSEP), are associated with a genetically inherited form of cholestasis called progressive familial intrahepatic cholestasis type 2 (PFIC2)." (PMID 37490339, 2023). "Such oestroprogestative induced cholestasis has been reported in female patients carrying a monoallelic variant in ABCB4 and ABCB11." (PMID 35626323, 2022). "Of note, induction of hepatic ER stress in cholestasis decreases gene expression of Cyp7a1, Fxr, Abcc3 and Abcb11 similar to the pattern observed in our study)." (PMID 35948878, 2022). "Overall, it is clear that FXR agonists in cholestasis act by directly transactivating genes such as ABCB11, but our data adds to regulatory complexity of this process as FXR agonists also act by blocking an inhibitory pathway mediated by miR-199a-5p." (PMID 34774795, 2021). "Moreover, an inherited mutation in the adenosine triphosphate (ATP)-binding cassette subfamily B (ABCB) 11 gene, which encodes for bile salt export pump (BSEP), may lead to the diminishing of the bile acids transport and clearance, potentially leading to cholestasis." (PMID 33732695, 2021). "The impairmentation of ABCB11 in humans with cholestasis and various animal models of intrahepatic and obstructive cholestasis lead to retention of bile acids in the hepatocyte and exacerbation of liver injury." (PMID 34774795, 2021). "The risk of cholestasis in pregnancy has been associated with genetic variants in ABCB4, ABCB11, ATP8B1, ABCC2, and TJP2 genes." (PMID 34557220, 2021). "Upregulation of ABCB11 in cholestasis is a possible mechanism protecting hepatocytes from bile acids accumulation, which is also related with simultaneous increase in other efflux transporters." (PMID 34117631, 2021). "Transient neonatal cholestasis has been reported with heterozygous mutations in both ABCB4 and ABCB11 (Bile Salt Exporter Protein)." (PMID 37207060, 2021). "In a model of estradiol-induced cholestasis, authors showed that following treatment with estradiol-17β-d-glucuronide (E217G), ABCB11 and ABCC2 are relocalized from canalicular membranes to intracytoplasmic compartments." (PMID 33672718, 2021). "The expression of ABCB11/Abcb11 is variably altered in various forms of experimental and human cholestasis and is dependent on etiology and duration." (PMID 34774795, 2021). "We report a 3-month-old male with cholelithiasis and transient neonatal cholestasis in the setting of combined pathogenic heterozygous mutations in the genes ABCB4 and ABCB11." (PMID 37207060, 2021). "In patients with ABCB11 (BSEP) deficiency, the cholestasis symptoms re-occurred after OLT due to an immune response inhibiting BSEP function." (PMID 33383947, 2020). "This revealed 8 AOPs linked to liver fibrosis, cholestasis and steatosis, and the associated MIE are defined by protein alkylation, LXR and inhibition of the bile salt export pump ABCB11." (PMID 32372211, 2020). "Defects in genes coding for bile salt transporter proteins (BSEP/ABCB11, FIC1/ATP8B1 and MDR3/ABCB4) cause cholestasis leading to the release of inflammatory cytokines, chronic inflammation and subsequent cholangiocarcinogenesis." (PMID 30819129, 2019). "Absence of ABCB11 and ABCB4 proteins related to mutations in the ABCB11 and ABCB4 gene causes PFIC2 and 3 and leads to severe cholestatic liver disease in children that results in development of progressive cholestasis and liver cirrhosis." (PMID 31886153, 2019). "Loss of functional ABCB11 and ABCB4 proteins causes early-onset refractory cholestasis or cholangiopathy." (PMID 31886153, 2019). "Stigmasterol has also been postulated to directly promote cholestasis through antagonizing FXR activity resulting in reduced Abcb11 expression." (PMID 29643332, 2018). "Missense mutations in BSEP/ABCB11 impair protein translation or intracellular trafficking, which reduce canalicular expression of BSEP and eventually cause cholestasis." (PMID 30367658, 2018).
cholestasis (continued). "Interestingly, in DSS/chow mice there was moderate suppression of Abcb11 mRNA at the 14-day time point and suppression of Abcc2 mRNA at the 7-day and 14-day time points, yet, importantly, this reduced transporter expression alone was insufficient to cause cholestasis." (PMID 29643332, 2018). "Concomitant with biochemical cholestasis, mRNA expression of Abcb11 and Abcc2 was significantly suppressed in DSS/PN14d mice." (PMID 29643332, 2018). "Cholestasis in pregnancy has been associated with genetic variants/mutations in ABCB4, ABCB11, ATP8B1, ABCC2 and TJP2." (PMID 30367658, 2018). "In early-stage cholestasis, expression levels of ABCB11 (BSEP), ABCC2 (MRP2), and SCLO-isoforms (OATP) where increased, suggesting that in situations of increased relative exposure to bile acids, human hepatocytes downregulate bile acid resorption." (PMID 30761355, 2018). "Some genetic forms of cholestasis have been found to be associated with specific mutations in the ABCB4 (MDR3) and ABCB11 (BEP) genes." (PMID 29221149, 2017). "In PFIC2 mutations within ABCB11, the gene encoding for the canalicular bile salt export pump (BSEP), lead to a defect in the extrusion of bile salts across the canalicular membrane of hepatocytes causing cholestasis." (PMID 25093717, 2014). "Heterozygous ABCB11 mutations have also been identified in cases of ICP (ICP2), drug induced cholestasis and transient neonatal cholestasis." (PMID 19133130, 2009). "These include low GGT as a cause of cholestasis, especially BA, and PFIC-2 (ABCB11 gene variants)." (PMID 41517312, 2025). "MYO5B is also required for proper localization of the bile salt export pump ABCB11 at the apical/canalicular plasma membrane of hepatocytes; its deficiency impairs the bile salt export pump function in the canalicular membrane, contributing to cholestasis." (PMID 40310351, 2025). "For example, TNF-α can inhibit the transcription of the tubule bile acid transporter Abcb11, bilirubin outlet Abcc2, and sterol transporter Abcg5/8 in intestinal inflammation, cholestasis, or the activation of hepatic macrophages, and thus affect the expression of transporters." (PMID 35163972, 2022). "In this study, we sought to determine whether miR-199a-5p contributes to the depletion of ABCB11/Abcb11 in cholestasis in mice." (PMID 34774795, 2021). "Similarly, the bile acid transporter ABCB11 (BSEP), which is inhibited by many drugs resulting in intracellular bile acid accumulation and cholestasis, was downregulated in most media." (PMID 34746700, 2021). "Furthermore, inhibition of ABCB11, in particular by accumulation of bile acids in the hepatocytes, has already been described for the development of cholestasis." (PMID 33466663, 2021). "Depending on the duration, ABCB11 mRNA and protein levels are depleted in human and experimental cholestasis, but the mechanisms underlying these changes have not been completely characterized." (PMID 34774795, 2021). "In contrast, common ABCB11 variants as well as its inhibition have been associated with transient cases of liver injury such as intrahepatic cholestasis of pregnancy, drug-induced liver injury (DILI), sepsis- and parenteral nutrition (PN)-induced cholestasis." (PMID 32646411, 2020). "Thereby, immunohistochemistry for ABCB11 and ABCB4 could be a useful diagnostic tool to determine the extent of cholestasis and disease progression in PSC." (PMID 31886153, 2019). "In addition to familial intrahepatic cholestasis, partial defects in ATP8B1, ABCB11, and ABCB4 predispose patients to drug-induced cholestasis and intrahepatic cholestasis in pregnancy." (PMID 30148122, 2018). "IL-1β increases hepatocyte NF-κB signaling, which interferes with farnesoid X receptor and liver X receptor bonding to respective promoters of canalicular bile and sterol transporter genes (Abcc2, Abcb11, and Abcg5/8), resulting in transcriptional suppression and subsequent cholestasis." (PMID 29643332, 2018).